CST1 (cystatin SN)
Diseases named in the same sentence as CST1 in open-access papers (continued):
Sharing a sentence is not in itself a finding about the gene and the disease.
lung carcinoma (7 papers, 2022 to 2025). "Cross‐cancer studies reveal that cystatin SN (CST1, SN), a metastasis‐associated molecule, shows aberrant overexpression in colorectal, breast, and lung cancers." (PMID 40919133, 2025). "Interestingly, there is emerging evidence linking CST1 to lung cancer." (PMID 40535419, 2025). "Incorporating five predictive variables—gender, nodule size, CST1, and GIMAP1-GIMAP5—into a binary logistic regression model, we aimed to predict the probability of lung cancer." (PMID 40535419, 2025). "For example, a high expression of CST1 is known as an unfavorable prognostic marker across tumors and experimentally induced EMT in lung cancers." (PMID 38203315, 2023). "We highlight the increased expression of immune-response-related genes FCGBP, BPIFB, F5, CST1, and CFB, and their correlation to epithelial-to-mesenchymal transition (EMT) under SMG, rendering them potential biomarkers of lung cancer progression." (PMID 36613598, 2022). "FCGBP, BPIFB1, F5, CFB, and CST1 and their correlation to EMT key markers displayed a potentially less metastatic phenotype of lung cancer under SMG." (PMID 36613598, 2022).
allergic rhinitis (6 papers, 2013 to 2025). Inflammation of the nasal mucous membranes caused by an IgE-mediated response to external allergens. "The CST1 mRNA has been reported to be upregulated in the nasal epithelia of patients with Japanese cedar-specific and other seasonal allergic rhinitis during the pollen season." (PMID 32577150, 2020). "Nevertheless, higher CCL3 concentration in serum could be observed in patients with allergic rhinitis, only seen for the samples overexpressing CST1." (PMID 38270326, 2024).
nasal polyps (5 papers, 2018 to 2023). "Supplementaryly, CST1 enhances eosinophil activation and recruitment by inducing IL-5 production in nasal polyp cells isolated from patients with eosinophilic chronic rhinosinusitis." (PMID 36776870, 2023). "Cystatin SN (CST1), a type 2 cystatin subfamily member, is highly expressed in nasal polyps from patients with intractable chronic rhinosinusitis with nasal polyps." (PMID 37628907, 2023). "In addition, the expression levels of CST1 in the nasal mucosa and nasal polyps of ACRSwNP patients were positively correlated (r = 0.850, p = 0.002), and the expression levels in the nasal epithelium and bronchial epithelium were also positively correlated (r = 0.454, p = 0.001)." (PMID 36059464, 2022).
periodontitis (5 papers, 2019 to 2025). An acute or chronic inflammatory process that affects the tissues that surround and support the teeth. "Based on the previous literature, CST1 expression has been linked to other oral disorders, such as periodontitis, where excessive proteolytic activation has been documented." (PMID 40869198, 2025). "The reduction of salivary cystatin SN in periodontitis patients could be associated with greater proteolytic damage to the periodontal tissues, with a subsequent progression of periodontal disease." (PMID 39620241, 2025). "In a cross‐sectional study, the concentration of cystatin SN (encoded by the CST1 gene on chromosome 20p11.2) was found to be depleted in periodontitis patients as compared to healthy controls, but still present in sufficient quantities to inhibit cathepsins H and L." (PMID 39620241, 2025). "According to the consistency analysis, cystatin SN was reported to be significantly elevated in healthy controls as compared to periodontitis patients in 3 out of the 13 studies included in our systematic review." (PMID 39620241, 2025). "Among these, complement C3, profilin‐1, SA100A8, and fibrinogen were consistently reported as increased in periodontitis, while cystatin‐SN and leukocyte elastase inhibitor were more elevated in periodontally healthy controls." (PMID 39620241, 2025). "The concentration of CST1 was found to be depleted in periodontitis patients when compared to healthy controls, but still present in sufficient amount to inhibit host-derived cysteine proteases." (PMID 37762137, 2023). "In the present study, severe periodontitis patients showed a markedly reduced expression of CST1 when compared to periodontally healthy individuals." (PMID 37762137, 2023). "If the level of the protein in salivary samples from gingivitis patients will be as high as that in periodontally healthy and successfully treated patients, CST1 should be regarded as a specific biomarker of periodontitis." (PMID 37762137, 2023). "Consistently, CST1 allowed the differentiation of patients with active periodontitis from both healthy subjects and treated periodontitis patients in the hierarchical cluster analysis." (PMID 37762137, 2023). "CST1 levels in saliva were able to separate patients with severe periodontitis from both healthy controls (with two exceptions) and treated periodontitis subjects (with one exception) who were clustered together." (PMID 37762137, 2023). "Complement C3, keratin (type I and type II), profilin‐1, S100A8, cystatin‐SN, alpha‐2‐macroglobulin, leukocyte elastase inhibitor, and fibrinogen were the proteins consistently over‐expressed or under‐expressed in periodontitis patients in at least three papers." (PMID 39620241, 2025). "In this context, CST1 has recently been reported to be downregulated in patients affected by severe forms of periodontitis, pointing toward the hypothesis that CST1 may serve as a general biomarker of oral cavity health." (PMID 40869198, 2025). "CST1 was negatively correlated with the percentage of pathological sites (p < 0.001) and was effective in discriminating active periodontitis from healthy periodontal status (whether H or T)." (PMID 37762137, 2023). "Depletion of CST1 in periodontitis patients, resulting in a reduction of their immuno-modulatory properties, could also contribute to the hyper-inflammatory response to pathogenic biofilm." (PMID 37762137, 2023). "Our results suggest that salivary CST1 could be regarded as a useful biomarker not only for the diagnosis periodontitis but also in monitoring the response after active periodontal treatment and during supportive periodontal care." (PMID 37762137, 2023). "Interestingly, in the present study, successfully treated periodontitis patients showed significantly higher salivary expression of CST1 than untreated patients and comparable with those of healthy controls." (PMID 37762137, 2023).
periodontitis (continued). "Within the limitations of the present study, CST1 could be regarded as a potential biomarker of periodontitis." (PMID 37762137, 2023). "Moreover, it would be interesting to investigate the expression of CST1 in what is regarded as the precursor of periodontitis, that is gingivitis." (PMID 37762137, 2023). "However, the picture is not entirely clear as other studies have shown reduced total cystatin activity and specific reductions in cystatin-SN and cystatin-S in periodontitis patients." (PMID 31511002, 2019). "However, it is not possible to establish if the depletion of CST1 in periodontitis patients was a consequence of the proteolytic activity of bacterial enzymes in the oral environment or a lower expression of the protein due to the complex interplay between the host and the pathogens." (PMID 37762137, 2023).
chronic rhinosinusitis (4 papers, 2023 to 2024). Chronic form of sinusitis. "Moreover, high levels of CLCs, chemokine (C-C motif) ligand 17, cystatin SN, interleukin (IL)-5, and macrophage inflammatory protein-1β in nasal secretions have been found to be associated with poor prognosis in chronic rhinosinusitis patients under surgical and conventional medical treatments." (PMID 36838965, 2023). "As CCL26 attracts eosinophils, this interaction is supported by previous studies showing that CST1 progresses the migration of eosinophils and might play a role in the development of chronic rhinosinusitis." (PMID 38270326, 2024).
esophageal cancer (4 papers, 2021 to 2024). A primary or metastatic malignant neoplasm involving the esophagus. "As a result, several studies have investigated the effects of CST1 expression on the cellular microenvironment, revealing a correlation between CST1 expression and migratory and invasive behavior of gastric and esophageal cancer cells." (PMID 37762137, 2023). "Since there are no better markers for esophageal cancer up to now, CST1 is worth considered as a diagnostic marker relatively." (PMID 38414741, 2024). "By analyzing the TCGA database data through the UALCAN website, we found that CST1 expression was significantly upregulated in esophageal cancer tissues compared with normal tissues, and closely correlated with grades, stages, and lymph node metastases of cancerous tissues." (PMID 36848349, 2023). "Additionally, a significant difference (p < 0.05) in the expression level of the CST1 gene was observed between esophageal cancer patients and individuals without the disease, as evidenced by data from the GEPIA database." (PMID 38414741, 2024). "There was no statistically significant distinction observed between the ESCC group and other EC groups (such as esophageal adenocarcinoma, sarcoma, endocrine carcinoma, etc.), suggesting that CST1 may not exhibit specific elevation in ESCC compared to other types of esophageal malignant tumors." (PMID 38414741, 2024).
non-small cell lung carcinoma (4 papers, 2017 to 2025). A group of at least three distinct histological types of lung cancer, including non-small cell squamous cell carcinoma, adenocarcinoma, and large cell carcinoma. "Furthermore, in non-small cell lung cancers (NSCLCs), patients with high CST1 expression show more serious recurrence/metastasis and poorer survival compared to low CST1 expressed counterparts." (PMID 29383149, 2017).
pancreatic cancer (4 papers, 2015 to 2021). "CST1 possibly contributes to the proliferation of cancer cells and acts as a potential biomarker for the early diagnosis of pancreatic cancers." (PMID 29383149, 2017). "Overexpression of CST1 was also correlated with malignancy-associated proteins such as PCNA, cyclin D1, cyclin A2 and cyclin E in pancreatic cancer cell line." (PMID 26569312, 2015). "Furthermore, CST1 also contributes to the proliferation of pancreatic cancer cells and acts a potential biomarker for the early detection of pancreatic cancers." (PMID 29383149, 2017). "Recent findings show that CST1 was highly expressed in colon, gastric and pancreatic cancers." (PMID 26569312, 2015).
endometrial cancer (3 papers, 2023 to 2025). Primary or metastatic malignant neoplasm involving the endometrium (mucous membrane that lines the endometrial cavity). "The diversity increased greatly from benign to high-grade endometrial carcinoma and the benign condition, low-grade endometrial carcinoma and high-grade clustered into CST1, CST 2, and both CST3 and CST4, respectively." (PMID 40041148, 2025).
hepatocellular carcinoma (3 papers, 2023 to 2025). A malignant tumor that arises from hepatocytes. "For hepatocellular carcinomas, CST1 was found to promote the process of EMT in tumor cells by regulating the PI3K/Akt pathway." (PMID 36848349, 2023).
lymph node metastasis (3 papers, 2017 to 2023). "In addition, a significant correlation was observed between CST1 expression and lymph node metastasis (P = 0.023), invasion depth (P < 0.001) and pTNM-stage (P < 0.001)." (PMID 34921160, 2021).
Alzheimer disease (2 papers, 2013 to 2024). A progressive, neurodegenerative disease characterized by loss of function and death of nerve cells in several areas of the brain leading to loss of cognitive function such as memory and language. "Model 1, which includes only the main effects, appeared to be the most concise and effective model for understanding the relationship between CST1 and Alzheimer’s disease risk." (PMID 39599575, 2024). "Overall, we believe our study remains exploratory, highlighting the potential impact of CST1 antibody levels on Alzheimer’s disease development." (PMID 39599575, 2024).
bladder cancer (2 papers, 2020 to 2025). "In bladder cancer tissues, CST1, CST2, CST6, CSTA, and CSTB were significantly upregulated, while CST3 and CST7 were downregulated compared to benign tissues." (PMID 40747123, 2025). "Our results revealed that CST1/CST2/CST6 genes were significantly upregulated, whereas CST3/CTS7 genes were downregulated in bladder cancers." (PMID 40747123, 2025).
glioma (2 papers, 2010 to 2020). A benign or malignant brain and spinal cord tumor that arises from glial cells (astrocytes, oligodendrocytes, ependymal cells).
lung adenocarcinoma (2 papers, 2022 to 2025). A carcinoma that arises from the lung and is characterized by the presence of malignant glandular epithelial cells. "Recent research has further revealed that elevated expression of CST1 is associated with lung adenocarcinoma and promotes epithelial–mesenchymal transition." (PMID 40535419, 2025). "By using prognostic analysis of Kaplan-Meier Plotterr and PrognoScan database, we found that high expression of CST1 was associated with poor prognosis in lung adenocarcinoma patients." (PMID 35637432, 2022). "In this study, we found that CST1 was highly expressed in lung adenocarcinoma and was associated with prognosis and tumor immune microenvironment." (PMID 35637432, 2022). "CST1 exhibited increased expression among the upregulated genes in lung adenocarcinoma tissues compared to lung tissues." (PMID 40535419, 2025). "Cell experiments confirmed that overexpression of CST1 promoted lung adenocarcinoma cells migration and invasion, while knockdown of CST1 significantly inhibited lung adenocarcinoma cells migration and invasion." (PMID 35637432, 2022). "Immunofluorescence results revealed that CST1 was primarily located in the cytoplasm of normal lung epithelial cells and lung adenocarcinoma cells, and the staining pattern was vesicular." (PMID 35637432, 2022). "In view of the consistent results obtained by enrichment analysis, we hypothesized that CST1 may play an important role in lung adenocarcinoma metastasis and invasion." (PMID 35637432, 2022). "Upon intersecting with the datasets GSE118370 and GSE140343, we identified that CST1 and GIMAP1-GIMAP5 were the only genes exhibiting significant differential expression in lung adenocarcinoma tissue compared to normal tissue." (PMID 40535419, 2025). "Specifically, CST1 was upregulated, whereas GIMAP1-GIMAP5 was downregulated in lung adenocarcinoma tissue when contrasted with normal tissue." (PMID 40535419, 2025). "In this study, we identified significant high expression of CST1, a member of the CST superfamily, in lung adenocarcinoma based on expression profiling from TCGA and GEO databases." (PMID 35637432, 2022). "Finally, we validated the clinical significance of CST1 and GIMAP1-GIMAP5 in patients with lung adenocarcinoma, particularly highlighting a strong correlation between GIMAP1-GIMAP5 expression levels and prognosis for patients." (PMID 40535419, 2025). "In summary, CT imaging and RNA sequencing analysis of benign and malignant nodules, combined with a nomogram, suggest that CST1 and GIMAP1-GIMAP5 are potential biomarkers for lung adenocarcinoma of GGNs, providing new insights into its pathogenesis and treatment." (PMID 40535419, 2025).
periodontal disease (2 papers, 2023 to 2025). "Further data are needed to confirm the current findings and to clarify if CST1 plays a role in the etiopathogenesis of periodontal disease and which is the molecular process underlying its expression across different clinical conditions." (PMID 37762137, 2023). "First, the cross-sectional design prevents us from establishing any conclusion on the causal and temporal relationship between active periodontal disease and the expression of CST1." (PMID 37762137, 2023). "Overall, CST1 plays an important role in the oral microenvironment, primarily by controlling in vivo proteolytic events, which are involved in the etiopathogenesis of periodontal disease." (PMID 37762137, 2023). "Therefore, salivary CST1 may be a promising non-invasive biomarker for periodontal disease diagnosis and monitoring." (PMID 37762137, 2023). "It is plausible that the lack, or even the reduction, of salivary CST1 may lead to higher levels of protease activity and may contribute to proteolytic destruction of the periodontal tissues, and a subsequent progression of periodontal disease." (PMID 37762137, 2023).
thyroid cancer (2 papers, 2021 to 2023). "Nevertheless, the significance of CST1 in thyroid carcinoma and the upstream regulator of CST1 remain to be determined." (PMID 33968941, 2021). "We demonstrated that ENO1 regulated CST1 expression and that these two proteins acted synergistically in thyroid carcinoma progression." (PMID 33968941, 2021). "To further clarify the relationship between ENO1 and CST1 in thyroid carcinoma, we combined overexpression and knockdown assays in TPC1 cells." (PMID 33968941, 2021). "Our study demonstrated that ENO1 was an oncogene in thyroid carcinoma that acted downstream of mTOR/HIF1α and accelerated thyroid carcinoma progression via regulating CST1." (PMID 33968941, 2021). "Importantly, CST1 silencing reversed the oncogenic function of ENO1 on thyroid carcinoma cell growth, migration and tumorigenic capacity." (PMID 33968941, 2021). "There was a positive correlation between ENO1 and CST1/CST4 in human thyroid carcinoma tissues." (PMID 33968941, 2021). "Furthermore, knockdown of CST1 reduced the migration capacity of thyroid carcinoma cells." (PMID 33968941, 2021). "In this study, we presented the data that ENO1 positively regulated the expression of CST1 and CST4 in thyroid carcinoma cells." (PMID 33968941, 2021). "In summary, although many complicated questions have not been answered, our study was the first to identify the mTOR/HIF1α/ENO1 pathway in thyroid carcinoma progression and ENO1 as a regulator of CST1, thereby paving the way for early diagnosis and efficient therapy of thyroid carcinoma." (PMID 33968941, 2021). "Next, we studied the role of CST1 and CST4 in thyroid carcinoma." (PMID 33968941, 2021). "Nevertheless, the role of CST1 in thyroid carcinoma has not yet been investigated." (PMID 33968941, 2021). "Functional experiments demonstrated that knockdown of CST1, but not CST4, suppressed the growth of growth of thyroid carcinoma cells." (PMID 33968941, 2021).
viral infections (2 papers, 2023 to 2024). "We can speculate that an overexpression of CST1 mimics a virus infection and causes therefore a downregulation of HLA‐F." (PMID 38270326, 2024). "However, a downregulation of MHC class I could be observed in human blood cell lines as well as the alveolar basal epithelial cell line A549 after the infection with influenza A and B,54 nevertheless, our cells overexpressed CST1 and had no virus infection." (PMID 38270326, 2024).
allergic asthma (1 paper, 2024). A asthma with a basis in a pathological type I hypersensitivity reaction. "Our results may indicate that the overexpression of CST1 and CCL26 causes a more severe airway inflammation, particularly in allergic asthma, as well as an impaired immune system." (PMID 38270326, 2024).
Ascites (1 paper, 2023). Accumulation of fluid in the peritoneal cavity (between the layers of the peritoneum that lines the abdomen). "As expected, ectopic expression of CST1 significantly increased the number of peritoneum xenograft tumors and the ascites volume in the abdominal cavity." (PMID 36369321, 2023).
co-infection (1 paper, 2025). "RAS exacerbation has been associated with the co-infection with various microorganisms, suggesting that CST1 deficiency might facilitate prolonged microbial-induced destruction of the oral mucosa during the RAS episodes." (PMID 40869198, 2025).